RAD50 (RAD50 double strand break repair protein)
Diseases named in the same sentence as RAD50 in open-access papers (continued):
Sharing a sentence is not in itself a finding about the gene and the disease.
tumor (continued). "Our study provided genetic evidence of interactions between INPP4B and RAD50, and deepened our understandings on the orchestrated genetic machinery governing tumor progression." (PMID 31872854, 2020). "Four variants of uncertain significance showed loss of heterozygosity in the tumor (ATM c.4709T>C; CHEK2 c.1036C>T; PALB2 c.1001A>G, and RAD50 c.281T>C), which is an indication of pathogenicity." (PMID 33134171, 2020). "Taken together, these themes support the interpretation that selection against Mre11 complex-dependent ATM signaling occurs during tumor progression, and that Rad50-dependent ATP metabolism is crucial for ATM activation by the Mre11 complex." (PMID 32187176, 2020). "Increased RAD50 expression has been found in multiple tumours, including breast cancer, ovarian cancer, lung cancer and rectal cancer 8-11." (PMID 32922536, 2020). "For example, RAD50 increases in colorectal cancer patients have been shown to be positively related to tumour development and prognosis." (PMID 32922536, 2020). "Rad50, Rad51, Rad54b, Mre11a, Palb2, Brca1 and Bard1 all showed significantly higher expression in resistant tumours compared to responding tumours (p = 0.05, p < 0.001, p < 0.001, p < 0.001, p = 0.002, p < 0.001 and p = 0.012 respectively)." (PMID 31080552, 2019). "Low RAD50 expression in the tumour periphery was also observed to be increased in patients needing adjuvant therapy." (PMID 30769804, 2019). "The genes most frequently targeted by MSI are RAD50 (16% of MSI-H tumours), ATR (15%) and RBBP8 (10%)." (PMID 28585546, 2017). "P130 a member of the Rb family that acts as a tumor suppressor is critical for telomere length control via forming a complex with Rad-50 to block telomerase-independent telomere lengthening." (PMID 29085821, 2017). "Additional Cox regression analyses confirmed that expression of RAD50 in early tumor stage and low-grade subgroups significantly correlated with DFS (HR = 0.218, 95% CI 0.084–0.570, p = 0.002)." (PMID 29189711, 2017). "Contrast to the IR alone (6.17 fold increase) or combined with Ad-EGFP treatment (5.23 fold increase), IR combined with Ad-RAD50 limited tumor growth (the tumor only acquired 2.73 fold crease, P = 0.011)." (PMID 26951044, 2016). "A combination of IR and mutant RAD50 therapy produced significant tumor cytotoxicity in vitro, with a corresponding increase in DNA damage, prevented proliferation and cell viability." (PMID 26951044, 2016). "By contrast, Ad-EGFP group tumors showed 7.0 fold increases in tumor volume (P > 0.05) and a single intratumoral injection of Ad-RAD50 induced a significant suppression of tumor growth relative to controls, with 5.23 fold increase in tumor volume (P > 0.05)." (PMID 26951044, 2016). "Cytoplasmic AEG-1 protein expression in the primary tumour was positively correlated to the phosphorylation of NF-κB/p65 at Ser 536 (p = 0.002), p73 (p = 0.033), and Rad50 (p = 0.024) as well as to the apoptotic rate (p = 0.006)." (PMID 22643064, 2012). "Whereas RAD50 c.687delT variant did not associate with any clinical tumor features, MCPH1 c.909_921del carriers had a significant enrichment of multifocal tumors (38% vs. 16% in non-carriers)." (PMID 40009290, 2025). "Our investigation aims to unravel potential associations with other non-BC or non-OC tumour types with pathogenic or likely pathogenic mutations (hereinafter, PVs) in the RAD50, RAD51C, RAD51D, and BRIP1 genes." (PMID 40282418, 2025).
tumor (continued). "As proven in the present study, the list of genes from the 44-gene panel more frequently mutated in BOT compared to the other tumor groups (FANCB, SEM1, FANCA, BRCA2, CHEK2, MUTYH, RAD50) was much longer than analogically altered genes in the hot-spot panel (KRAS only)." (PMID 39456660, 2024). "In addition, both tumor cohorts with poor and good responses to neoadjuvant treatment presented mutations in ARID1A, CREBBP, BRCA2 and RAD50, although with significantly different frequencies." (PMID 37373240, 2023). "Among them, the enhanced binding of MRE11:p.K464R mutation to RAD50/RPS3 facilitated non-homologous end joining (NHEJ) repair in tumor cells, thereby expanding the scope of research into acquired resistance to PARP inhibitors." (PMID 37759323, 2023). "With respect to MB, not only has it been sporadically described in NBS patients, but heterozygous germline or somatic NBN, RAD50 and MRE11 mutations were discovered in MB patients, implying their potential role as haploinsufficient tumour suppressors for MB development." (PMID 35839783, 2022). "Whilst the role of PALB2 and ATM is fairly well established in PC, RAD50 is not among the genes generally associated with this tumour." (PMID 34034685, 2021). "We next assessed the potential role of Rad50 on tumour growth and metastasis in vivo." (PMID 34734468, 2021). "In the ER+ cohort, similarly, low nuclear RAD50 was also significantly linked with poor BCSS (p = 0.0002) but not in ER− tumours (p = 0.370)." (PMID 34782604, 2021). "Moreover, in the TCGA cohorts, the expression of RAD50 in tumour tissues is significantly higher than that in normal tissues." (PMID 32922536, 2020). "NGS and IHC analyses of the tumor revealed multiple defects in DDR genes and proteins, specifically, heterozygous truncating mutations in CHK1, FANCM, RAD50, POLD1, and FANCP; compound heterozygous truncating mutations in ARID1A; and loss of ATM and ARID1A protein by IHC." (PMID 32568634, 2020). "In the study, the analysis of the data from the two cohorts supported our hypothesis and clearly demonstrated the high expression of RAD50 in tumour tissues from HCC patients, which results in increases in the HCC recurrence rate and poor overall survival." (PMID 32922536, 2020). "Similarly, low RAD50 expression in early tumor stage and low-grade tumor subgroups was significantly associated with worse OS (p < 0.001)." (PMID 29189711, 2017). "We discovered that low levels of RAD50 expression at early tumor stages and low-grade tumor subgroups were significantly associated with worse DFS and OS, indicating a relationship between postoperative tumor expression of RAD50 and prognosis." (PMID 29189711, 2017). "Additionally, we assessed the influence of RAD50 expression on other relevant tumor clinico-histopathological variables such as perineural invasion." (PMID 29189711, 2017). "We correlated postoperative RAD50 tumor expression with patient DFS and OS." (PMID 29189711, 2017). "Although speculative, this list could include other key HDR genes including ATM, BRCA1/2, MRE11, RAD50, NBS1 or RAD51, which are also mutated in CRC and many other tumor types." (PMID 26318585, 2015). "These loss-of-function RAD50 mutations could restrict MRE11-mediated degradation of nascent DNA at challenged replication forks in PARP-resistant, BRCA1/2-PALB2-mutated cells, and may help to explain tumor chemoresistance." (PMID 35501303, 2022). "The authors of this study showed that weak RAD50 expression was associated with poor prognosis in patients with MSS CRC, and postulated that increased RAD50 expression in MSS CRC could be a tumor suppressive cellular response to prevent further tumor progression." (PMID 29189711, 2017). "However, in multivariate Cox analysis with OS, perineural invasion (HR = 1.701, 95% CI 1.036–2.792, p = 0.036) remained significantly associated with OS, but not with tumor RAD50 expression (HR = 0.712, 95% CI 0.462–1.095, p = 0.122)." (PMID 29189711, 2017).
tumor (continued). "When patients were grouped into early tumor stage (T1–2) and low-grade (G1–2) subgroups, low expression of RAD50 was associated with decreased DFS (p = 0.001), indicating that RAD50 may be a useful prognostic biomarker for early tumor stage and low-grade subgroups." (PMID 29189711, 2017). "Moreover, Ad-RAD50 combined with IR produced a dramatic tumor regression in human NPC xenografts." (PMID 26951044, 2016). "It is known that RAD50 complex associates with TRF2 in the S phase of cell cycle, which suggests that this predicted interaction may promote telomere maintenance in tumor cells in order to allow tumor cells to divide indefinitely." (PMID 21777411, 2011). "In our study, AQB was found to inhibit CBPt-induced expression of key proteins in the HRR cascade, including MRE11, RAD50, P-CHK1, P-CHK2, and RAD51, leading to DNA damage accumulation and promoting tumor cell death." (PMID 41353219, 2025). "We initially compared the total expression levels of ERBB2, RAD21, RAD50 and BARD1 mRNA in normal and tumor bladder tissues with bioinformatics analyses using the TCGA database (Cohort one)." (PMID 37474724, 2023). "The data reflect the importance of Rad50 ATPase activity for Tel1/ATM activation and suggest that inactivation of ATM signaling confers an advantage to burgeoning tumor cells." (PMID 32187176, 2020). "The expression of MRE11, RAD50 and NBS1 proteins in the TP (tumor, n = 261; normal, n = 258) were also tested, resulting in an average ROC-AUC of 0.862." (PMID 30176843, 2018). "Together with MRE11 and NBS1, RAD50 is part of the MRN complex, which is heavily involved in maintenance of genomic integrity and tumor suppression." (PMID 29189711, 2017). "In paired t test analysis, all of the 4 genes (RAD50, RTEL, TERC and TRF1) showed significant expression (dCt) difference between tumor and normal tissues (with corrected P values of 1.22E-16, 7.78E-05, 1.08E-11 and 5.05E-13 respectively)." (PMID 28424414, 2017). "The MRN complex comprising of DNA repair proteins MRE11, RAD50 and NBS1 (MRE11/RAD50/NBS1) detects and repairs double-strand breaks, and is therefore critical for maintaining genomic integrity and suppressing tumor progression." (PMID 29189711, 2017). "RAD50, RTEL, and TRF1 also showed significant difference of expression between tumor and normal tissues in TCGA data but with higher expression in tissues." (PMID 28424414, 2017). "Furthermore, from the IHC findings that showed both low levels of MRE11 and RAD50 were linked with higher grade tumours, the identification of aldo–keto reductase family in both RAD50 low and MRE11 low tumours highlights a role in tumour progression." (PMID 34782604, 2021). "There was a non-significant trend of better survival in tumours with high cytoplasmic expression of RAD50." (PMID 35006434, 2020). "Expression levels of MRE11, RAD50 and NBS1 proteins in the TC were tested using a forward and reverse binary logistic regression analysis in an immunohistochemical scoring data set from 262 tumor samples and 258 normal tissues." (PMID 30176843, 2018). "The primary tumor of HGG15 had no detectable driver SNVs, however, it acquired an ATRX frameshift mutation as well as a RAD50 missense mutation at recurrence." (PMID 29084603, 2017).
tumor (continued). "Selected CRC target genes involved in apoptosis (BAX), tumor growth (TGFβRII), WNT pathway (AXIN2, TCF4, WISP3), DNA repair (ATM, ATR, BLM, BRCA1, BRCA2, DNAPKcs, MBD4, MRE11, MSH3, MSH6, RAD50, XRCC2) and PI3-kinase signaling (PTEN) were analyzed for mutations in MSI-positive HGG samples." (PMID 21637783, 2011). "However, it was observed that MYCN is a transcriptional regulator of MRE11, RAD50, and NBS1, and the MRN complex contributes to the control of DNA damage levels compatible with tumor cell survival, so that high MRE11 expression is related to reduced overall survival in primary human neuroblastoma." (PMID 34201502, 2021). "Thus, it is possible that ectopic expression of Rad50 may recruit CARD9 and contribute to tumour metastasis through activating NF‐κB pathway in HGSOC." (PMID 34734468, 2021). "In the analysis of the 4 significantly hyper-methylated genes (RAD50, RTEL, TERC and TRF1), all of their expression levels were lower in tumor than the matched normal tissues, which suggested a negative correlation trend between methylation and expression." (PMID 28424414, 2017).
infection (12 papers, 2014 to 2025). The state of being infected such as from the introduction of a foreign agent such as serum, vaccine, antigenic substance or organism. "It was implied that the enhanced sensitivity of NPC cells to IR via Ad-RAD50 infection is also associated with abrogating DSBs induced G2/M arrest." (PMID 26951044, 2016). "As cccDNA reaches a relatively stable level 3–5 days after HBV infection in HepG2-NTCP-K7 cells, we transiently knocked down RAD50 at 5 days post infection (dpi)." (PMID 39752632, 2025). "Because we observed an increase in Rad50 recruitment to replicated viral DNA when infection was carried out in the presence of PCNA-I1, we wanted to confirm these findings via immunofluorescence." (PMID 37486931, 2023). "Adenoviral transgene induction in CNE1 infected with Ad-RAD50 (MOI = 50) was confirmed by visualizing green report gene expression under fluorescence microscopy 12 h after infection." (PMID 26951044, 2016). "At 24 h after infection with Ad-RAD50, the Mre11 and Nbs1 proteins were also significantly downregulated in cells treated with Ad-RAD50 alone or combing with 4Gy IR." (PMID 26951044, 2016). "The infection of Ad-RAD50 induced a downregulation of the wild-type Rad50 protein in CNE1 cells and 5–8 F cells." (PMID 26951044, 2016). "As expected, Ad-RAD50 infection significantly increased IR induced inhibition the capacities of CNE1 and 5–8 F cells’ colony formation." (PMID 26951044, 2016). "Our data suggested that infection with Ad-RAD50 increases the sensitivity of NPC cells to IR, likely by shortening the length of their telomeres." (PMID 26951044, 2016). "It was confirmed by that mutant RAD50 expressed, MRN-deficient cells exhibited cell growth inhibition by MTT assay in vitro, and by the colony formation assay that Ad-RAD50 infection brought out obviously decrease in NPC cells survival fraction after IR." (PMID 26951044, 2016). "Cells treated with Ad-RAD50 infection, and Ad-RAD50 infection plus 4Gy IR exhibited co-localization of the signals representing wild-type Rad50 (blue) and Mre11 (red), suggesting the interaction between these two proteins (-b)." (PMID 26951044, 2016). "Moreover, the disruption of wild-type Rad50 by infection with the mutant-Rad50 repressed the levels of wild-type Rad50, Mre11 and Nbs1." (PMID 26951044, 2016). "We hypothesized that the infection of Ad-RAD50 would reduce the DSBs repair capacity of the NPC cells, thereby resulting in enhanced cytotoxicity in cells treated with combined Ad-RAD50 infection and IR, and this reduced DSBs repair capacity would be the result of the abrogation of the G2/M arrest." (PMID 26951044, 2016). "At the same time, upregulation of key components that catalyze end-processing and ligation, namely, RAD50, ARTEMIS, XRCC4, and LIG4, was observed upon infection." (PMID 33339161, 2020). "We observed that 24 h post infection, MRE11 was found downregulated, whereas RAD50, CTIP, and ATM were found upregulated in a CagA-independent manner." (PMID 33339161, 2020). "Levels of the other components of the MRN complex, RAD50 and NBS1, remain unchanged during MVM infection." (PMID 29088070, 2017). "To understand the mechanism by which LLO dampens the DDR we investigated the effect of infection and the effect of the purified LLO toxin on the host proteins, Mre11, RAD50 and NBS1, involved in sensing DNA breaks." (PMID 25340842, 2014). "Infection of HeLa cells with all three serotypes led to decreased levels of MRE11 and Rad50." (PMID 28791251, 2017). "Consistent with aniPOND data, Rad50 was recruited to viral DNA in the presence and absence of PCNA-I1, with an apparent increase in recruitment to replication compartments when infection was carried out in the presence of PCNA-I1." (PMID 37486931, 2023).
infection (continued). "Expression and steady-state levels of all analyzed cellular proteins (β-actin, USP7, Daxx, Rad50, Nbs1, Mre11, and PML) were not altered in UBM2 H5pm4250 versus WT H5pg4100 infection." (PMID 35254132, 2022). "Infection with Ad5 mutants lacking different E4 genes demonstrated that there was no degradation of MRE11 and Rad50 when cells were infected with Ad5 specifically lacking E4orf6–E1b55K." (PMID 28791251, 2017).
genetic disorder (3 papers, 2017 to 2025). "This study identifies and characterizes a novel type of splicing mutation in RAD50 deficiency, a rare genetic disorder." (PMID 39666384, 2024). "Our findings help to characterize human RAD50 deficiency and uncover an unusual splicing mutational mechanism with potential relevance for other human genetic diseases." (PMID 39666384, 2024).
CNS tumors (1 paper, 2017).
myopathy (1 paper, 2020). A disease of the muscle in which the muscle fibers do not function properly. "The variant c.3050 G > A (p.Trp1017Ter) in RAD50 in a boy presenting for myopathy." (PMID 31937788, 2020).
neurological disorders (1 paper, 2021). "In addition to homozygous causal variants in ASPM or CENPJ, we discovered additional heterozygous modifier variants in WDR62, CEP63, RAD50 and PCNT—genes already known to be associated with neurological disorders." (PMID 34068194, 2021).
RAD50 also shares sentences with these, for which no sentence is quoted: acute myeloid leukemia (3 papers); allergic disease (2); ataxia-telangiectasia-like disorder (2); breast and (2); Burkitt lymphoma (2); colorectal adenocarcinoma (2); eczema (2); lymphoma (2); non-Hodgkin lymphoma (2); oral cancer (2); skin cancer (2); xeroderma pigmentosum (2); adult onset asthma (1); Allergy (1); Alzheimer’s disease (1); atopic eczema (1); B cell lymphomas (1); bladder tumour (1); central nervous system diseases (1); Clear cell renal cell carcinoma (1); COVID-19 (1); diffuse large B-cell lymphoma (1); enterocolitis (1); familial breast cancer (1); glioblastoma (1); hay fever (1); hepatocellular carcinoma (1); hereditary cancer predisposing syndrome (1); Hereditary Cancer Syndromes (1); hereditary colorectal cancer (1).
A further 23 diseases each share a sentence with RAD50 in 1 paper.